TWIST1 (twist family bHLH transcription factor 1)
Diseases named in the same sentence as TWIST1 in open-access papers (continued):
Sharing a sentence is not in itself a finding about the gene and the disease.
cancer (continued). "TWIST1 expression induces malignant properties such as initiation, stemness, and invasion of cancer." (PMID 37534184, 2023). "Twist-related protein 1 (Twist1), a basic helix-loop-helix transcription factor associated with EMT, is related to metastasis of many cancer cell types." (PMID 36781842, 2023). "Twist family bHLH transcription factor 1 (Twist1) is highly up-regulated in various human malignant tumors and plays a crucial role in facilitating the epithelial–mesenchymal transition (EMT) process through multiple signaling pathways." (PMID 38202657, 2023). "Next, we measured the Twist1 expression in ccRCC tissues and their adjacent non-carcinoma tissues, and the results showed that the mRNA and protein levels of Twist1 significantly increased in ccRCC tissues compared to normal control tissues." (PMID 36639679, 2023). "In other cancer types, the transcription factor TWIST1 promotes miR-10b expression, and the activation of TWIST1 protein by phosphorylation is PKA dependent." (PMID 35482409, 2022). "Remarkably, conditional deletion of Twist1 in MuSCs is sufficient to suppress cancer-induced muscle wasting." (PMID 35441960, 2022). "Transient overexpression of TWIST1 activates a subset of mammary epithelial cells with stem cell-like properties and the whole process of cancer metastasis." (PMID 36123378, 2022). "The embryonic transcription factors TWIST1/2 are frequently overexpressed in cancer, acting as multifunctional oncogenes." (PMID 35022561, 2022). "In humans, TWIST1 plays vital oncogenic roles in various cancers including the generation of cancer cell stemness, drug resistance, epithelial-mesenchymal transition (EMT), and metastasis." (PMID 36115849, 2022). "TWIST1 promotes cancer metastasis by regulating epithelial mesenchymal transition (EMT) and is critical for the maintenance of EMT-associated CSC-like characteristics." (PMID 36123378, 2022). "In cancer cells, TWIST1 targets several enzymes from the DNA damage response pathway, thus neutralizing senescence and cell death." (PMID 36559182, 2022). "TWIST1 is involved in all the stages of cancer metastasis and its expression contributes to metastasis and invasion by inducing the EMT." (PMID 36200046, 2022). "The stability of TWIST1 is a vital step in maintaining the cancer stem-like cell features of castration-resistant prostate cancer." (PMID 36123378, 2022). "Here we identify a role for TWIST1 in the establishment of ESCC cancer stem cell (CSC)-like phenotype, facilitating the transformation of non-CSCs to CSCs." (PMID 36474162, 2022). "Consistently with previous studies, our results indicate that SALL4 in concert with other stemness markers like OCT4, NANOG, and SOX2 can drive reprogramming of cancer cells toward a CSC-like phenotype mediated by the TWIST1 expression." (PMID 36474162, 2022). "TWIST1 encodes a basic helix-loop-helix transcription factor that contributes to EMT, a key process in the metastases formation of cancer." (PMID 35308229, 2022). "To extend the cellular effect of NDG1 to molecular presentations, we determined the expression of cancer stemness-associated regulators (ABCG2, Twist1, BMI1, NES, c-Met) in NDRG1-FL-transfected HNC cells." (PMID 35563887, 2022). "TWIST proteins are elevated during cancer progression and TWIST1 has been shown to diminish intercellular adhesion by decreasing epithelial E-cadherin expression and promoting mesenchymal Fibronectin, N-cadherin, and Vimentin expression." (PMID 36139386, 2022). "Among the upregulated microRNAs, we focused on miR-186-5p for its important contribution to EMT and chemoresistance in other cancer settings and because one of its targets, TWIST1, is an important factor in MPM progression and a target of butein." (PMID 36176750, 2022). "The TWIST1 gene is involved in epithelial–mesenchymal transition and is involved in several cancers, including AML." (PMID 36139405, 2022).
cancer (continued). "CRIPTO1 has been implicated in cancer epithelial cells’ plasticity and it regulates EMT together with TWIST1, SNAIL, and SLUG." (PMID 36474162, 2022). "Epithelial-mesenchymal transition (EMT) inducing transcription factor TWIST1 plays a vital role in cancer metastasis." (PMID 36115849, 2022). "UBCH10, a cancer-related E2 ubiquitin-conjugating enzyme, is highly expressed in human lung SCCs and upregulates the expression of Twist1, c-Myc, and Sox2." (PMID 36270982, 2022). "Our findings displayed that in TNBC cancer tissues, the TWIST1 protein level was markedly increased in comparison with the level in associated adjacent normal tissues." (PMID 35802537, 2022). "We conclude that K73 of TWIST1 is critical for TWIST1 stabilization, thus promoting cancer cell migration and invasion." (PMID 36115849, 2022). "Recently, several researches have exhibited the importance of TWIST1 in the genesis and progression of cancer." (PMID 35802537, 2022). "Our findings are consistent with a recent publication showing that TWIST1 interacts with tight junction protein 1 (TJP1) along the cell membrane of two different cancer cells." (PMID 35781329, 2022). "The TWIST1 transcription regulator plays an essential role in cancer metastasis and is activated by a variety of signal transduction pathways, including protein kinase B (PKB/Akt), STAT3, mitogen-activated protein kinase (MAPK), Ras, and Wnt signaling." (PMID 36559182, 2022). "The results of this study are consistent with previous reports demonstrating that FoxO1 inhibited Twist1 mRNA expression in cancer cells." (PMID 33772986, 2022). "TWIST1 is a phosphoprotein with multiple residues that are phosphorylated by several kinases according to numerous cancer studies." (PMID 35781329, 2022). "It has been reported in other cancer types that miR-10b is transcriptionally activated by the Twist1 transcription factor, and we identified a ~3-fold increase of TWIST1 expression in FLC." (PMID 35482409, 2022). "In BC, Twist1 is described as the master regulator of metastasis; however, several issues involving its role in different types and stages of human cancers remain to be addressed, particularly in BC subtypes." (PMID 34830027, 2021). "Over the ability to promote EMT, cancer progression and invasion, TWIST1 also has a relevant role in the reduction of the sensitivity to chemotherapy in some CRC cell lines." (PMID 34768901, 2021). "The main pathological functions attributed to Twist1 in human cancers are related to invasion and metastasis by promoting EMT in solid tumors." (PMID 34830027, 2021). "Hybridization experiments show that only a fraction of stromal cells expressing TWIST1 also shares the same genetic alterations of cancer cells." (PMID 34768901, 2021). "ADQ showed potential anti-cancer effects through regulation of the Akt pathway and Twist1 protein level in our study." (PMID 34408201, 2021). "The observation that harmine induces Twist1 degradation and therefore inhibits cancer cell invasion provides a possible alternative approach." (PMID 33626096, 2021). "The results reveal that TWIST1 inhibition leads to decreased macrophage recruitment to AT84 cancer cells." (PMID 33466385, 2021). "Transcription factors known to regulate EMT include ZEB1, ZEB2, SNAI1 (SNAIL), SNAI2 (SLUG), and TWIST1 and have been suggested to promote cancer progression, including metastasis." (PMID 34339740, 2021). "Twist1 has also been shown to be involved in the evasion of apoptosis and acts as a marker for cancer stem cells." (PMID 34572796, 2021). "TWIST1 is overexpressed in many advanced cancers and its expression levels have been correlated with poor outcomes." (PMID 33466385, 2021). "Numerous studies have demonstrated that aberrant overexpression of EMT-inducing genes, such as Twist1, Snail1, Snail2, Zeb1, Zeb2, N-cadherin, and the master stemness gene Notch1, triggers cell de-differentiation and cancer stem cell genesis." (PMID 34922602, 2021).
cancer (continued). "Widely reported as a transcription factor and an oncogene, TWIST1 promots many cancer metastases and progressions by regulating multiple genes." (PMID 34224315, 2021). "To mechanistically address this issue, we generated a cancer cell-specific, dual deletion of both Snai1 and Twist1 by crossing SnailcKO; YFPLSL mice with KPC; TwistcKO; YFPLSL mice (KPC;ST)." (PMID 33852841, 2021). "Twist1 expression induces a morphological change associated with EMT and significantly elevates cancer stem cell-like traits in MCF-7 and cervical cancer HeLa cells." (PMID 33768509, 2021). "Since ADQ showed a sufficient reduction of Twist1 at 5 μM in our study, this suggests that ADQ is efficient in suppressing Twist1 levels and can be developed as a drug candidate for treating multiple cancer types." (PMID 34408201, 2021). "As an example, we observed that TWIST1, one of the least commonly occurring proteins and a well-known oncogene, was exclusively present in only 25 diseases and over 50% of them were cancers." (PMID 34197603, 2021). "Akt2, which is closely related to Twist1 in the EMT process, has also been associated with cancer resistance." (PMID 33768509, 2021). "The down-regulation of Twist1 leads cancer cells to be sensitive to doxorubicin by suppression of MDR1 and EMT." (PMID 33768509, 2021). "Many transcription factors had a main role in cancer metastasis, such as Zeb1, Twist1, Slug, and Snail1." (PMID 33923474, 2021). "When Twist1 is overexpressed in cisplatin and doxorubicin-resistant cancer cells, it modulates Y-box-binding protein-1 as a downstream target." (PMID 33768509, 2021). "Similar to Snail, SCP1 interacts with and dephosphorylates Ser68 of Twist1, leading to the acceleration of Twist1 degradation and inhibition of cancer invasion." (PMID 33808323, 2021). "The invasive ability of cancer cells was found to be decreased by the regulation of Twist1 protein levels." (PMID 33567682, 2021). "The miR-29 family has been used to investigate Twist1-mediated cancer metastasis in HNSCCs (NCT01927354)." (PMID 33917482, 2021). "Epithelial‐to‐mesenchymal transition (EMT) and EMT‐transcriptional factors (TFs) are correlated with cancer metastasis, and our previous study indicated TQ inhibited TWIST1 and EMT‐related makers." (PMID 34609056, 2021). "Using Aurora A-as7 kinase, we have identified several direct targets, including PHLDA1, LIMK2, ALDH1A1, SPOP, YBX1, and TWIST1, in cancer cells." (PMID 34066036, 2021). "Recently, a positive correlation between NF-κB and activated EMT-related transcription factors, such as TWIST1 and Slug, was described in several human cancers." (PMID 33945104, 2021). "Confirming the well-documented role of Twist1 in cancer, the functional enrichment analysis described EMT as the most altered biological process." (PMID 34830027, 2021). "Because of the increasing relevance of IL-17 signaling in cancer biology, we focused our investigation on the role of Twist1 in this signaling pathway." (PMID 34830027, 2021). "This makes it relatively safe to target Twist1 in the treatment of cancers such as metastatic breast cancer." (PMID 33626096, 2021). "In a review report, overexpression and role of TWIST1 were observed in various cancers such as prostatic cancer, gastric cancer, breast cancer, and CRC." (PMID 33752711, 2021). "In this study, we found that the cccDNA level was associated with the expression of Twist1, an important transcription factor associated with EMT, a process required for cancer cell metastasis." (PMID 33572617, 2021). "TWIST1 is a master transcriptional regulator of the epithelial to mesenchymal transition (EMT), and a high level of TWIST1 is a prognostic marker indicative of poor cancer outcomes." (PMID 33298572, 2020).
cancer (continued). "A survey of literature suggests the hypermethylation of the associated proteins, including PIK3R5, TBX2 and TWIST1 individually, have multiple biological functions in various cancers, and could serve as potential methylation targets to screen for onset of different cancers." (PMID 33143142, 2020). "Another EMTTF, Twist1, inhibited cancer cell plasticity, dissemination, and lung metastasis in a mouse model of (oncogene-induced) BC." (PMID 33297508, 2020). "Together, MYC and Twist1 induce the cancer cell to secrete cytokines like Ccl2 and Il13 that lead to recruitment and polarization of macrophages respectively, thus causing metastasis." (PMID 31933479, 2020). "Along these lines, both genetic and pharmacological inactivation of Twist1 function was highly significant at protecting against cancer cachexia, which translated into a significant survival benefit in the experimental PDAC animals." (PMID 32655411, 2020). "For example, ectopic expression of Snail/Twist1 in cancer cells results in the changes of the surface marker to a stem-like phenotype (CD44high/CD 24low) and enhances the mammosphere-forming ability." (PMID 32143517, 2020). "TWIST1 belongs to the basic helix-loop-helix (bHLH) transcription family, which is involved in cancer metastasis and flanks the CDH1 gene to repress E-cadherin." (PMID 31963305, 2020). "The EMT is a key process in driving cancer metastasis, with several transcription factors including Twist1, Snail, and ZEB1 cooperating to control this complex process." (PMID 32391253, 2020). "Although TWIST1 has been known for its role cancer progression, two other studies with fly and axolotl system demonstrate that TWIST1 is implicated with skeletal muscle regeneration." (PMID 32011235, 2020). "TWIST1 is a bHLH transcription factor known for its role in epithelial-to-mesenchymal transition during mesenchymal development and in cancer progression." (PMID 31917787, 2020). "Both MYC and TWIST1 are overexpressed in multiple human cancers, suggesting there is a common embryonic transcriptional program they regulate in the embryonic microenvironment which is hijacked by cancer cells." (PMID 31933479, 2020). "Transient overexpression was preferred over stable expression as a model to mimic the heterogeneous upsurge in the levels of Twist1 during cancer progression." (PMID 32337580, 2020). "Expression of Twist1 is elevated in various human cancers, including cancers of lung, breast, prostate and liver." (PMID 32549341, 2020). "TWIST1 is a major driver of EMT, and EMT is often associated with metastasis, stemness, and drug resistance in many cancers, including PCa." (PMID 33227047, 2020). "Taken together, these results suggest that Twist1 expression is highly correlated with EMT in various cancers." (PMID 32337580, 2020). "Recently, we have shown that induction of Twist1 is also related to muscle cachexia during the progression of cancer." (PMID 32655411, 2020). "The cancer types LGG (Brain), KIPAN (Pan Kidney) and PRAD (prostate) showed a significant positive correlation with Twist1 expression for somatic mutation and for CNA events in LGG." (PMID 32337580, 2020). "Collectively, our results clearly show that AKT-mediated phosphorylation of TWIST1 is essential TWIST1-induced gene induction and cancer cell metastasis." (PMID 32922123, 2020). "While these lines are not isogenic, they provide a model for studying the repression of TWIST1 in cancer cell lines that is potentially mediated by expression of the E2 protein." (PMID 33298572, 2020). "There is some evidence that TWIST1 promotes the metastatic dissemination of cancer cells and induces chromosomal instability." (PMID 32629858, 2020). "In cancer, TWIST1 has been shown to be involved in epithelial–mesenchymal transition and to promote metastasis." (PMID 32183222, 2020).
cancer (continued). "We examined if MYC and TWIST1 cooperated in human tumorigenesis by examining 9502 human patients with 33 different cancers from a TCGA study and 144 HCC patients with metastatic HCC." (PMID 31933479, 2020). "Here, we demonstrate that E2 represses expression of the TWIST1 gene; an elevated level of this gene is a marker of poor prognosis for a variety of cancers." (PMID 33298572, 2020). "Increased expression of TWIST1 and vimentin in cancer tissues, as well as a decreased expression of programmed cell death factor 4 (PDCD4), and E-cadherin expression is all linked with malignant tissue degree." (PMID 32268527, 2020). "TWIST1 plays a central role in regulating EMT in the cancer microenvironment, influencing the transition of NFs to CAFs with CXCL2 as the target for transcription." (PMID 32268527, 2020). "EMT can be induced in a number of ways, including by pleiotropically acting EMT-TFs including SNAI1/2 (Snail1/2), ZEB1/2 and TWIST1/215, these have been shown to have a role in cancer." (PMID 32269211, 2020). "TWIST1 has been found to be involved in promoting cell migration through up-regulating the expression of MMPs in cancer cells." (PMID 32595631, 2020). "Twist1 promotes epithelial-mesenchymal transition, invasion, metastasis, and chemotherapy resistance in cancer cells and thus is a potential target for cancer therapy." (PMID 32655411, 2020). "Overexpression of Tβ4 has been proved to enhance cell proliferation, invasion, and expression of epithelial-to-mesenchymal transition (EMT)-inducing transcription factor, Twist-related protein 1 (Twist1) in cancer cells." (PMID 32245208, 2020). "TWIST1 belongs to a family of transcriptional factors highly expressed in most cancers, and particularly in those highly metastatic." (PMID 33040091, 2020). "The finding that Twist1 overexpression consistently downmodulates levels of checkpoint regulators further underscores the role of Twist1 in aggravating CIN in cancers." (PMID 32337580, 2020). "EMT transcription factors Twist1, Snail1 and Six1 would influence carcinoma cells by inducing EMT characteristics and aggressive properties." (PMID 31931858, 2020). "Both Snail1 and Twist1 are key transcription factors that meditate EMT in cancer, and Snail1 is a key suppressor for E-cadherin." (PMID 30902084, 2019). "Simultaneously, the expression of metastatic markers, such as Slug, Twist1 and vimentin, in primary cells derived from the malignant tumors, was higher than in metastatic nodules." (PMID 31450740, 2019). "FLG interacts with MCL1, USP1, C21orf59, MAK, and KIR3DS1 and mucin interacts with ERBB3, SNAI1, TWIST1, TWIST2, and CDH2, all of which, IPA predicted to be associated with cancer." (PMID 31058088, 2019). "TWIST1 has been shown to be responsible for maintaining the Mes phenotype and cell survival in suspension in several cancer types." (PMID 30548372, 2019). "Our results suggest that doxorubicin has a dual action: it kills cancer cells, but simultaneously induces TWIST1 expression leading to EMT of the surviving cells." (PMID 31331001, 2019). "Given that Twist1 can promote invasive properties of cancer cells, we next examined the role of Twist1 in salinomycin-mediated blockage in migration and invasion." (PMID 31718679, 2019). "In the last set of experiments of this work, we tested the expression of some microRNAs known to play different roles in cancer, directly or indirectly related to TWIST1." (PMID 31331001, 2019). "Twist1 has been suggested to have oncogenic properties and the expressions of miR-16 and Twist1 in cancer cells and tissues were inversely correlated." (PMID 31572802, 2019).